MMACHC (metabolism of cobalamin associated C)
Description:
Cobalamin (vitamin B12) cytosolic chaperone that catalyzes the reductive decyanation of cyanocob(III)alamin (cyanocobalamin, CNCbl) to yield cob(II)alamin and cyanide, using FAD or FMN as cofactors and NADPH as cosubstrate. Cyanocobalamin constitutes the inactive form of vitamin B12 introduced from the diet, and is converted into the active cofactors methylcobalamin (MeCbl) involved in methionine biosynthesis, and 5'-deoxyadenosylcobalamin (AdoCbl) involved in the TCA cycle. Forms a complex with the lysosomal transporter ABCD4 and its chaperone LMBRD1, to transport cobalamin across the lysosomal membrane into the cytosol. The processing of cobalamin in the cytosol occurs in a multiprotein complex composed of at least MMACHC, MMADHC, MTRR (methionine synthase reductase) and MTR (methionine synthase) which may contribute to shuttle safely and efficiently cobalamin towards MTR in order to produce methionine. Also acts as a glutathione transferase by catalyzing the dealkylation of the alkylcob(III)alamins MeCbl and AdoCbl, using the thiolate of glutathione for nucleophilic displacement to generate cob(I)alamin and the corresponding glutathione thioether. The conversion of incoming MeCbl or AdoCbl into a common intermediate cob(I)alamin is necessary to meet the cellular needs for both cofactors. Cysteine and homocysteine cannot substitute for glutathione in this reaction.
Synonyms: DKFZP564I122; cblC
Tractability: Small molecule: a structure with a bound ligand is known; it has a binding pocket of medium quality.
Gene: Protein-coding gene on chromosome 1 (45,500,300 to 45,513,382, forward strand). Ensembl gene ENSG00000132763.
Subcellular location: Cytoplasm, cytosol
Subcellular location (Human Protein Atlas): Nucleoplasm; Cytosol; Plasma membrane
Pathways (Reactome):
Disease: Defective MMACHC causes MAHCC; Defective MMADHC causes MMAHCD
Metabolism: Cobalamin (Cbl) metabolism
Gene Ontology:
Molecular function: cyanocobalamin reductase (cyanide-eliminating) (NADP+) activity; demethylase activity; FAD binding; glutathione binding; oxidoreductase activity; protein binding; protein homodimerization activity; transferase activity, transferring alkyl or aryl (other than methyl) groups
Biological process: cobalamin metabolic process; demethylation; glutathione metabolic process
Cellular component: cytoplasm; cytosol; nucleoplasm
Genetic constraint (gnomAD): Loss-of-function variants: 14 observed, 18.83 expected, observed/expected ratio (o/e) 0.74, 90% interval 0.49 to 1.16. The upper end of that interval is the gene's LOEUF score, 1.16, which puts it in group 5 of 6, group 1 being the genes least tolerant of losing a copy. Missense variants: 392 observed, 384.96 expected, observed/expected ratio (o/e) 1.02, 90% interval 0.94 to 1.11. Synonymous variants: 151 observed, 149.93 expected, observed/expected ratio (o/e) 1.01, 90% interval 0.88 to 1.15.
Gene-disease validity (ClinGen):
ClinGen rates the evidence that MMACHC causes each of these diseases.
methylmalonic aciduria and homocystinuria type cblC (autosomal recessive): Definitive.
Homologues: Orthologues: chimpanzee MMACHC (99% identical), macaque MMACHC (96% identical), rabbit MMACHC (90% identical), mouse Mmachc (84% identical), guinea pig MMACHC (83% identical), rat Mmachc (82% identical), dog MMACHC (79% identical), pig MMACHC (68% identical), tropical clawed frog mmachc (49% identical), zebrafish mmachc (42% identical), Caenorhabditis elegans cblc-1 (29% identical).
Diseases named in the same sentence as MMACHC in open-access papers:
MMACHC is named in the same sentence as 43 diseases in open-access papers, as found by Europe PMC text mining. Sharing a sentence is not in itself a finding about the gene and the disease. The quoted sentences say what the papers report.
Methylmalonic aciduria (21 papers, 2013 to 2026). Increased concentration of methylmalonic acid in the urine. "Mutations in the MMACHC gene lead to autosomal recessive combined methylmalonic aciduria and homocystinuria (cblC type)." (PMID 42002808, 2026). "It is worth noting that genetic testing for methylmalonic acidurias must consider epi-cblC, and pathogenic variants must be searched for in MMACHC and PRDX1." (PMID 40565527, 2025). "MMACHC gene deficiency leads to autosomal recessive methylmalonic aciduria combined with hypercystinuria." (PMID 40735484, 2025). "The aim of this study was to characterize the variable phenotypes and outcomes associated with the methylmalonic aciduria and homocystinuria type C protein gene (MMACHC) c.482G > A mutation in 195 Chinese cases with CblC disease." (PMID 38070096, 2024). "Out of these groups, the most prevalent is CblC disease, caused by mutations in the MMACHC gene affecting the synthesis of AdoCbl and MeCbl, which results in combined methylmalonic aciduria (MMA) and homocystinuria (HCU)." (PMID 38137438, 2023). "Recently, combined homocysteinaemia with methylmalonic aciduria due to pathogenic recessive variants in the MMACHC gene has been highlighted as a treatable cause of HSP." (PMID 33646413, 2021). "Biallelic variants in MMACHC results in the combined methylmalonic aciduria and homocystinuria, called cobalamin (cbl) C (cblC) deficiency." (PMID 33473346, 2021). "A mutation on the MMACHC gene, known to be associated with methylmalonic aciduria and homocystinuria cblC type, was also found." (PMID 33804237, 2021). "Combined methylmalonic aciduria and homocystinuria (cobalamin C deficiency, cblC) is a well‐described disorder of vitamin B12 metabolism caused by mutations in the MMACHC gene with multisystemic manifestations." (PMID 32905057, 2020). "All patients had methylmalonic aciduria, homocysteinemia, compound heterozygous MMACHC gene mutations were detected in all patients, and 7/8 patients with c.482G>A mutation." (PMID 33324334, 2020). "Two novel variants of the MMACHC gene were identified, and prenatal genetic diagnosis is an accurate and convenient method to help avoid the delivery of combined methylmalonic aciduria and homocystinuria patients." (PMID 30157807, 2018). "Furthermore there is a pathogenic variant in the MMACHC gene which is associated with methylmalonic aciduria and homocystinuria." (PMID 34977425, 2022). "Methylmalonic aciduria and homocystinuria type C protein (MMACHC) is required by the body to metabolize cobalamin (Cbl)." (PMID 38137438, 2023). "Released Cbl is exported from the lysosomes via the Lysosome Membrane Chaperone 1 (LMBD1) where it binds to methylmalonic aciduria type C and homocystinuria (MMACHC) proteins and then shuttled to cytoplasmic methionine synthase (MTR) and mitochondrial MUT." (PMID 35931118, 2022). "One infant diagnosed as having methylmalonic aciduria (MMA) using NeoSeq, was compound heterozygous for a pathogenic variant in the MMACHC gene (c.80A>G and c.567dup)." (PMID 34794485, 2021).
homocystinuria (18 papers, 2015 to 2026). An autosomal recessive inherited metabolic disorder caused by mutations in the CBS, MTHFR, MTR, and MTRR genes. "89% of the cases were MMA with homocystinuria (cblC) type caused by MMACHC gene mutation, and 11% of cases were isolated MMA caused by MUT mutation." (PMID 38355526, 2024). "Several pathogenic variants of the MMACHC gene have been reported to cause combined methylmalonic acidemia with homocystinuria." (PMID 38137438, 2023). "first mapped the cblC locus and identified mutations in the MethylMalonic Aciduria (Cobalamin deficiency) cblC type, with Homocystinuria (MMACHC gene, OMIM*609831)." (PMID 31470807, 2019). "In the present study, MMACHC mutations were analyzed in 10 pedigrees of combined methymalonic aciduria and homocystinuria (cblC type) and a novel mutation was identified." (PMID 26149271, 2015). "Combined methylmalonic aciduria and homocystinuria, cobalamin(cbl)C deficiency, is a rare disorder of intracellular vitamin B12(cbl) metabolism caused by mutations in the MMACHC gene." (PMID 26149271, 2015). "Two novel MMACHC variants were identified, and prenatal genetic diagnosis is an accurate and convenient method that helps avoid the delivery of combined methylmalonic aciduria and homocystinuria patients." (PMID 30157807, 2018). "Besides, from cblC type MMA, there are many genetic disorders with a high incidence and hotspot mutations in specific population, such as c.1006C > T mutation in CBS gene mutation of homocystinuria in Qatar, and c.394C > T mutation in MMACHC gene cobalamin C defect in North India." (PMID 35069678, 2021). "All patients had methylmalonic acidemia and homocystinuria and an inconclusive molecular diagnosis for the MMACHC gene." (PMID 34215320, 2021). "Combined methymalonic aciduria and homocystinuria consists of four subtypes, MMACHC(cblC), MMADHC (cblD combined, cblD-MMA and cblD-HCY), LMBRD1(cblF) and ABCD4(cblJ)." (PMID 26149271, 2015). "MMACHC epimutation/PRDX1 mutation analyses should be part of routine genetic testing for all patients presenting with a metabolic phenotype that combines methylmalonic aciduria and homocystinuria." (PMID 34215320, 2021). "Herein, we report the molecular analysis of 11 Italian probands, with a diagnosis of methylmalonic aciduria and homocystinuria between 2008 and 2018, who had previously been tested with MMACHC gene sequencing without reaching any conclusive molecular diagnosis." (PMID 34215320, 2021).
cblC (16 papers, 2018 to 2026). "In contrast, six Pakistani newborns were found to be homozygous for the pathogenic variant c.394C > T in the MMACHC gene associated with cobalamin C deficiency." (PMID 40700042, 2025). "One child (P8) showed elevated tHHcy and urine methylmalonic acid levels, attributed to cobalamin C deficiency caused by MMACHC variants (c.482G>A, c.609G>A)." (PMID 40994713, 2025). "Our study reported six Pakistani newborns with the same homozygous pathogenic variant c.394C > T in the MMACHC gene associated with cobalamin C deficiency." (PMID 40700042, 2025). "MMACHC (metabolism of cobalamin associated C) mutation with c.609G > A is most frequently observed in patients with cobalamin C deficiency (cblC)." (PMID 39135208, 2024). "Among them, cblC (also known as cobalamin C disease or cblC disease) is the most common inherited disorder of cobalamin (vitamin B12) metabolism, caused by the MMACHC mutation located on chromosome 1p34.1." (PMID 38355526, 2024). "The MMACHC gene is the cause of the cblC type, which is the most common subtype always accompanied by homocysteine, of which, the main toxic effect is arterial wall injury; it further reduces the compliance of extracerebral intracranial arteries." (PMID 37226122, 2023). "In contrast, the adult epi-cblC patient in our study had the MMACHC:c.617G > A p.(Arg206Gln) variant." (PMID 34215320, 2021). "Previously reported epi-cblC patients are compound heterozygous for a genetic variant and a secondary epimutation at the MMACHC locus." (PMID 34215320, 2021). "Until now, nine epi-cblC patients have been reported, all of whom with a mono-allelic MMACHC epimutation and a MMACHC genetic variant affecting the other allele." (PMID 34215320, 2021). "Consistently, our early onset epi-cblC cases had MMACHC truncating variants (nonsense or the c.271dupA) known to be associated with early onset cblC." (PMID 34215320, 2021). "Although the genetic epidemiological data on CblC deficiency are limited, the carrier prevalence of the MMACHC mutation has been deduced to be 1/28–31 from the reported cblC incidences in the population in Shandong province, China." (PMID 32746869, 2020). "Cobalamin C deficiency (cblC) caused by the MMACHC mutations is the most common type of the disorders of intracellular cobalamin metabolism." (PMID 32746869, 2020). "Over 75 MMACHC mutations have been detected in cblC diseases, among which c.271dupA and c.331C > T are the most common for early-onset cblC and c.394C > T was associated mainly with the late-onset subtype." (PMID 31092259, 2019). "Consistently, treatment of fibroblasts from one of our epi-cblC cases with 5-AZA restored bi-allelic MMACHC expression with detection of the wild-type allele." (PMID 29302025, 2018). "Among these, the cblc type caused by MMACHC gene mutations is the most common form." (PMID 40830795, 2025). "MMACHC variant c.80A > G may be associated with prominent renal complications in Chinese cblC patients." (PMID 36704130, 2022). "In addition, among five reported Chinese cases with child- and adolescence-onset cblC-associated renal disease and genetic diagnosis, all of them had MMACHC heterozygous variant c.80A > G." (PMID 36704130, 2022). "CblC was diagnosed by the increasing of methylmalonic acid and total homocysteine in amniotic fluid and MMACHC c.609G > A homozygous mutation in amniocytes at the gestational age of 20 weeks." (PMID 32746869, 2020). "This type is called epi-cblC and can be due to bi-allelic PRDX1 mutations causing MMACHC epimutation, or it can be digenic with heterozygous PRDX1 and MMACHC pathogenic variants located in trans." (PMID 42002808, 2026). "Among these, the blc CblC type caused by MMACHC gene mutations is the most common form." (PMID 40830795, 2025). "In contrast, epi-cblC cases harbor an epimutation with an aberrant methylation of the CpG island (CpG:33) in the MMACHC promoter that silences the expression of the MMACHC gene." (PMID 35440018, 2022).
cblC (continued). "We observed only one subject in the control population with the same hypermethylation of the MMACHC sites as was reported in the epi-cblC cases and their relatives." (PMID 29302025, 2018). "The RNA-seq data analysis showed that the readthrough transcription of PRDX1 was prolongated through the MMACHC/CCDC163P bidirectional promoter and the TESK2 promoter in fibroblasts of epi-cblC patients." (PMID 35440018, 2022). "We unraveled the methylome architecture of the CCDC163P/MMACHC CpG island (CpG:33) and the TESK2 CpG island (CpG:51) by studying the epigenome-wide DNA methylation profile of the 17 epi-cblC cases." (PMID 35440018, 2022).
methylmalonic acidemia (12 papers, 2015 to 2025). A genetically heterogenous inherited disorder characterized by abnormalities in the metabolism of lipids and proteins. "Among combined methylmalonic acidemia cases in China, MMACHC gene mutation is the most common, accounting for approximately 99% of cases, and the most common mutant subtype is c.609G>A (p.W203X), followed by c.80A>G (p.Q27R) and c.658-660delAAG (p.K220del)." (PMID 36777632, 2023). "Genetic analysis was performed in 13 confirmed cases, among which 11 cases carried mutations in the MMACHC gene, suggesting that mutations in the MMACHC gene are the predominant cause of methylmalonic acidemia in Jining." (PMID 29731766, 2018). "MMACHC deficiency leads to combined methylmalonic acidemia and homocysteinemia." (PMID 40527782, 2025). "Methylmalonic acidemia, phenylketonuria, and primary carnitine deficiency were the major IEMs and the mutations in PAH, SLC22A5, and MMACHC genes are the leading causes of IEMs resulting in phenylketonuria, primary carnitine deficiency, and methylmalonic acidemia, respectively, in Jining area." (PMID 29731766, 2018). "Two of these cases were methylmalonic acidemia combined with homocysteinemia, carrying four types of mutations in the MMACHC gene, and studies have shown that c.609G > A may be the hot spot mutation carried in local patients with concurrent methylmalonic acidemia." (PMID 39670100, 2024). "Some hotspot mutations were observed for several IEMs, including PAH gene c.728G>A for phenylketonuria; MMACHC gene c.609G>A and c.567dupT, MMUT gene c.323G>A for methylmalonic acidemia and SLC25A13 gene c.852_855del for citrin deficiency." (PMID 33514801, 2021). "Pathogenic mutations in the MMACHC and MUT genes were detected in 11 and 2 cases of methylmalonic acidemia, respectively." (PMID 29731766, 2018). "We detected a heterozygous MMACHC gene mutation (c.656_658delAGA, p.K220del, OMIM# 277400) in P74 and a heterozygous MMACHC gene nonsense mutation (c.609G>A, p.W203*, OMIM# 277400) in P75 who previously bore a child with Methylmalonic Acidemia." (PMID 26274329, 2015). "Four mutation types of the MMACHC gene (e.g., c.609G > A (p.Trp203Ter), c.567dupT (p.Ile190fs)) and six mutation types of the MMUT gene (e.g., c.729_730insT (p.Asp244fs)) were found for methylmalonic acidemia." (PMID 39670100, 2024).
homocysteinemia (8 papers, 2011 to 2025). "Most reports show that MMA with homocysteinemia caused by MMACHC gene mutation is a common type of MMA in mainland China." (PMID 39670100, 2024). "Among the seven patients who were diagnosed with MMA and homocysteinemia, homozygotic or compound heterozygous MMACHC mutations were found in four of them, which suggested type CblC." (PMID 31969166, 2020). "MMA can be classified into two common types: isolated MMA and combined MMA and homocysteinemia, which are caused by deficiency in the MUT or MMACHC gene, respectively." (PMID 30728829, 2018). "Combined MMA and hyperhomocysteinemia, cblC type, is the most common inherited disorder of cobalamin metabolism, and the related gene, MMACHC, is located at 1p34.1." (PMID 30728829, 2018). "These two sites are hotspot mutations in the MMACHC gene in the Chinese population, and may also be hotspot mutations for cardiovascular complications in MMA and homocysteinemia." (PMID 40830795, 2025).
cobalamin deficiency (5 papers, 2016 to 2025). "To verify that reduction in MMACHC levels translate into a cobalamin deficiency, we derived mouse embryonic fibroblasts (MEFs) from RoninF80L/F80L mice and determined that MeCbl and AdoCbl coenzyme forms are greatly reduced." (PMID 35013307, 2022). "Together, lower availability of B2 and glutathione might reduce MMACHC function, leading to a functional cobalamin deficiency, a known effect of MMACHC defects." (PMID 26742069, 2016). "The complementation groups cblC, cblD and cblX are caused by mutations in the MMACHC (methylmalonic aciduria (cobalamin deficiency) cblC type, cblC), MMADHC (methylmalonic aciduria (cobalamin deficiency) cblD type, cblD) and the HCFC1 (host cell factor C1, cblX) genes." (PMID 27061115, 2016).
developmental delay (2 papers, 2022 to 2025). "The common clinical manifestations of MMACHC gene mutations include developmental delay, intellectual disability, hypotonia, visual impairment, and hematological manifestations." (PMID 40735484, 2025).
melanoma (2 papers, 2018 to 2024). A malignant, usually aggressive tumor composed of atypical, neoplastic melanocytes. "Melanomas and cell lines derived from melanoma often exhibit a higher occurrence of elevated methylation in the MMACHC promoter compared to other cancer types." (PMID 39125597, 2024).
congenital idiopathic nystagmus (1 paper, 2025). "Additionally, MMACHC itself may be a susceptibility gene for motor or congenital idiopathic nystagmus." (PMID 40565527, 2025).
Epileptic encephalopathy (1 paper, 2023). A condition in which epileptiform abnormalities are believed to contribute to the progressive disturbance in cerebral function. "The HCFC1 variants within the proteolysis domain disrupted the proteolytic processing with loss of growth suppression but did not affect MMACHC expression that was associated with cobalamin disorder and severe epileptic encephalopathy." (PMID 37264743, 2023).
hemolytic-uremic syndrome (1 paper, 2021). Acute kidney injury associated with microangiopathic hemolytic anemia and thrombocytopenia. "Hemolytic uremic syndrome (HUS) with genetic mutation of MMACHC, THBD, and DKGE is characterized by similar activation of the coagulation system." (PMID 34208103, 2021).
leukemia (1 paper, 2022). A malignant (clonal) hematologic disorder, involving hematopoietic stem cells and characterized by the presence of primitive or atypical myeloid or lymphoid cells in the bone marrow and the blood. "Simultaneous MMA and leukemia may be associated with abnormal amino acid levels and changes in blood microenvironment, or may be related to the genetic variation of MMACHC and MTR C. 2756 and the subsequent decrease of MTR activity." (PMID 35495149, 2022).